CD4 (CD4 molecule)
Diseases named in the same sentence as CD4 in open-access papers (continued):
Sharing a sentence is not in itself a finding about the gene and the disease.
tumor (continued). "The slower tumor growth and the extended survival in the CD4+ T cell-depleted mice may stem from the CD4-independent activation of some CD8+ T cells, which can inhibit the growth of implanted tumor cells." (PMID 22348070, 2012). "The HSP scavenger receptor system may permit presentation of antigens to—and activation of both CD4+ and CD8+ T cells—DC licensing and a fully activated CD8+ T cell capable of killing tumor cell targets." (PMID 23056925, 2012). "Taken together these data indicate that while CD4 T cell help is not required for the recruitment of Mam-A specific CD8 T cells to the tumor site and additional help does not enhance the functional ability of the Mam-A specific CD8 T cells." (PMID 22911764, 2012). "We therefore compared the number of tumor infiltrating high avidity T cells to the number of CD4+Foxp3+ Tregs in the tumor of vaccinated mice with and without Cy treatment." (PMID 22359647, 2012). "While CD4 effector infiltration and proliferation were only increased by CTLA-4 blockade, α4-1BB did increase inflammatory cytokine production from these cells both in the periphery and within the tumor itself." (PMID 21559358, 2011). "Studies by other groups have demonstrated that CD4 T cells and/or NK1.1+ cells contribute to tumor protection in B16 tumor-bearing mice treated with anti-CD25, which could explain the absence of detectable CD8 T cell responses." (PMID 22046294, 2011). "As we have previously published, CD8 T cell responses to TRP-2 were not naturally primed in B16 tumor-bearing mice that did not receive anti-CD4 treatment." (PMID 22046294, 2011). "We found that in LLC+Py mice, there was a dramatic increase in the density of tumor-infiltrating CD45+ cells, and when tumor-infiltrating lymphocyte subsets were examined, both CD4+ and CD8+ T cells populations were increased with CD8+ T cells representing the dominant cell type." (PMID 21931708, 2011). "In this study, we systematically investigated clinical importance of T-cell subsets infiltrating into human RCC tissues and found that the high density of tumour-infiltrating CD45RO+ as well as CD4+ T cells have negative impact on patient survival." (PMID 21934683, 2011). "Global attribution of the smaller clones of CD4 T cells to a response or tumor phenotype is not possible with the current data sets." (PMID 21573129, 2011). "Furthermore, increasing numbers of CD4+ (P = 0.008) and CD20+ lymphocytes in tumor (P = 0.006) correlated significantly with an improved DSS in patients with wide resection margins (n = 108)." (PMID 21298041, 2011). "Activated CD4+ T cells produce an array of cytokines leading to the generation and clonal expansion of tumor-specific CD8+ T cells with cytolytic activity which recognize and kill tumor cells." (PMID 21931708, 2011). "TIDC phenotype in RAG1−/− mice was not significantly affected by the transfer of purified CD8+ T cells or CD4+CD25+ Treg one day before tumor inoculation (data not shown)." (PMID 21390236, 2011). "In B16.OVA tumors, ∼14% of the CD4+ T cell population was Foxp3GFP+, as opposed to the ∼10% observed in the tumor-draining and non-draining LN, and their frequency increased during tumor growth." (PMID 21390236, 2011). "Maturation of tumor RNA-pulsed DCs with autologous CIK cells enhanced antitumor immunity, which could be induced by increased CD4+ Th1 and CD8+ T cells and decreased CD4+ CD25+ regulatory T cells." (PMID 24212972, 2011). "We also found that ablation of the CD4 T cell compartment allowed homeostatic expansion of polyclonal CD8 T cells, which has been shown by other groups to contribute to the preferential recognition of tumor antigens by CD8 T cells." (PMID 22046294, 2011). "In a mouse tumor model, activated or antigen-specific CD4+ Tregs did not inhibit CD8 proliferation and their differentiation to CTL, but blocked CTL killing." (PMID 21799858, 2011).
tumor (continued). "CD4+CD25+ Tregs are a subset of regulatory T cells with potent inhibitory effects on innate and adaptive immunity both in physiological and pathological status which play important roles in tumor evasion and metastasis." (PMID 22110525, 2011). "In vivo antibody depletion experiments suggested that CD8+ and NK cells, but not CD4+ cells, were the main effector cells responsible for the observed anti-tumor activity." (PMID 21689407, 2011). "Conversely, the EZH2-reactive CD4 T-cell clones were unable to recognize naturally processed epitopes derived from tumor cell lysates via DCs (data not shown)." (PMID 22053850, 2011). "In contrast to our data, IL-18 treatment did not change tumor infiltration of CD4+ T cells or macrophages, and reduced the number of CD8+ T cells." (PMID 21935389, 2011). "As previously reported using both low and highly immunogenic models, no CD4+ OTII T cell proliferation was detected in tumor-bearing mice." (PMID 21390236, 2011). "Both the TM40D and TM40D-MB tumor groups had decreased splenic levels of CD4+ and CD8+ T cell populations as compared to unchallenged mice, although the reduction in the TM40D-MB group was significantly more pronounced (CD4+P = 0.003, CD8+P = 0.012)." (PMID 21695190, 2011). "Flow cytometry analysis showed that CD4 + cells represented between 88–98% of the cells derived from whole tumor (data not shown)." (PMID 21573129, 2011). "We finally asked if Foxp3-negative CD4 or CD8 T cells, adoptively transferred into tumor-bearing mice, could be induced to express this transcription factor." (PMID 22112546, 2011). "A possible explanation lies in that Th17 CD4+ T cells can be unstable and may evolve into IFN-γ-producing Th1-like cells capable of promoting tumor destruction." (PMID 21943203, 2011). "Most significant was the demonstration that the CD4 T-cell clones generated by STEAP281-296 and EZH295-109 were capable of recognizing naturally processed antigen directly on HLA-DR expressing tumor cells and that the T-cells exhibited cytotoxicity against the tumor cells." (PMID 22053850, 2011). "There did not appear to be any appreciable difference among the various clinical outcomes with respect to patient age or gender, CD4 cell count, tumor type or size, nor location of tumor." (PMID 21437186, 2011). "The biology CD4 T cell population in these Pmel mice have not been studied; we noted an increased percent expression of Foxp3 in CD4s from both control and tumor-bearing mice, and to a comparable degree." (PMID 22112546, 2011). "We conclude that the defective presentation of B16.OVA tumor antigen by tumor-infiltrating dendritic cells and in the tumor-draining lymph node is not due to the presence of “natural” CD4+CD25+ Treg." (PMID 21390236, 2011). "Only low percentages of IFN-γ production against the tumor cell lines was observed in TCR transgenic CD4+ T cells without the addition of CD8." (PMID 21892941, 2011). "Therefore, antigen presentation through MHC class II is essential for the activation of antigen-specific CD4+ T cells and the induction of potent CD8+ CTL responses against tumor." (PMID 21048993, 2010). "These cells derive from purified CD8+ T lymphocytes (homogenously negative for CD4 expression) stimulated three-four times in MLTCs with the autologous tumor cells." (PMID 20711505, 2010). "Through this process, TAAs can be presented by the DC to both CD4+ and CD8+ T cells (in MHC I), and a broad and strong immune response against tumor could be induced." (PMID 21197274, 2010). "The lack of IL-2 production by both CD8+ and CD4+ T cells in these experiments is also consistent with an impaired anti-tumor response." (PMID 21203522, 2010).
tumor (continued). "Of note, the transfected cells were recognized by the p41–49-specific T cells but not the p37–51-specific CD4+ T cells, confirming that the p41–49 peptide can be endogenously processed and presented by tumor cells." (PMID 20981248, 2010). "Regardless of the tumor type, the animals with high proportions of CD4+ and low CD8+ T-cells had decreased survival rates." (PMID 20525350, 2010). "It was also shown that CD4+ CD25+ cells were preferentially concentrated in tumor mass rather than in tumor draining lymph nodes." (PMID 21318181, 2010). "However, the protective effect was abolished when both CD4+ and CD8+ cells were depleted, and all mice developed tumours in a timeframe similar to that in unimmunized animals." (PMID 20657846, 2010). "Using specific CD4+ and CD8+ cells against tumor antigens may provide another way of fighting cancer." (PMID 21318181, 2010). "CD4+ T cells contribute to antitumor immunity through diverse mechanisms, in which they are required not only for the maintenance of CD8+ CTLs but also for the infiltration of CD8+ CTLs at the tumor site." (PMID 21048993, 2010). "When tumor antigens were recognised by antigen presenting cells(APC), they were processed as peptides, and these peptides presented by APC acted as first and second signals to activate naive CD4+T cells and CD8+T cells." (PMID 21029461, 2010). "Finally, the prime boost strategy was able to reduce immunosuppressive CD4+CD25+Foxp3+ regulatory T cells (Tregs) in the spleen and tumor of vaccinated mice." (PMID 21067607, 2010). "We also demonstrate that immunotherapy aimed at stimulating immune response does not change proportions of Treg and effector CD4+ T cells in tumor-bearing mice." (PMID 21049016, 2010). "In contrast, CD4+ T cells expressing TCRs utilized by hybridomas #31 and 26 were not expanded in tumor draining lymph nodes and tumors." (PMID 21049016, 2010). "Moreover, CCL5 has been shown to be secreted by CD4+ T cells, recruits CCR5+ dendritic cells to the tumor location, and activates them through CD40-CD40L interactions." (PMID 21318181, 2010). "In the current study, we observed that treatment with CRT/E7 DNA in combination with imiquimod leads to decrease in the number of myeloid-derived suppressor cells but not CD4+CD25+ T cells in the tumor microenvironment of tumor-bearing mice." (PMID 20426849, 2010). "The involvement of systemic immunity in mediating antitumor effects was confirmed by (a) induction of tumor-specific CTL response, (b) IFN-γ secretion by splenocytes, and (c) infiltration of CD4+ and CD8+ T cells in tumors that secreted tumor reactive chemokines." (PMID 21067607, 2010). "Tumors from vaccinated mice were infiltrated with CD4+ and CD8+ T cells, resulting in the production of chemokines, which were consistent with the ability of effector cells and molecules to play a role in tumor regression mechanisms." (PMID 21067607, 2010). "That these effects occurred in the absence of tumor cell-T cell contact negated the possibility of tumor contact-dependent CD4+ T cell apoptosis and highlighted PGE2 as an important mediator of impaired cellular immunity in patients with cancer." (PMID 19812686, 2009). "We observed that, of the Jak proteins and associated Stat proteins, phosphorylations of Jak-3 and Stat-5 were down regulated in CD4+ T cells by tumor-shed PGE2, which could be ameliorated by pre-treatment of the tumor cells with theaflavins." (PMID 19812686, 2009). "Since these helper T cells play critical roles in the optimal induction and maintenance of clinically beneficial tumor immunity, here we address the role tumor-derived PGE2 might have on CD4+ T cell survival." (PMID 19812686, 2009). "All the reactions so far defined occurred independent of direct contact of CD4+ cells with tumor cells or even proximity thereby pointing towards the possibility of the presence of tumor-shed soluble immunosuppressors in the supernatant." (PMID 19812686, 2009).
tumor (continued). "The direct cytotoxicity of CD4 T cells against tumor has not been firmly established, however, studies have shown that cyotoxic CD4 T cells can be induced that play an important role in clearance of pathogens, such as EBV and CMV infections." (PMID 19707583, 2009). "There is accumulating evidence indicating that CD4+CD25+FoxP3+ regulatory T-cells (Treg) are able to induce tolerance to self-antigens and may also inhibit anti-tumour immune response." (PMID 19732435, 2009). "In high-grade serous tumors from optimally debulked patients, positive associations were seen between intraepithelial cells expressing CD3, CD4, CD8, CD45RO, CD25, TIA-1, Granzyme B, FoxP3, CD20, and CD68, as well as expression of MHC class I and II by tumor cells." (PMID 19641607, 2009). "In addition, FCs were effective in activating CD4+ and CD8+ T cells able to produce IFN-γ and inducing cytolysis of autologous tumor or semiallogeneic targets by a MHC class I-restricted mechanism." (PMID 18793383, 2008). "By day 10 of cultures, PBMCs primed using UV-irradiated tumor cells demonstrated a higher percentage of activated CD8+/CD4- T lymphocytes than non-primed PBMCs or PBMCs primed using mitomycin-treated MM cells." (PMID 18439316, 2008). "Direct killing of tumour cells occurs through the function of CD8 T cells, but the killing may be enhanced through the activation of CD4 T cells." (PMID 18728665, 2008). "Furthermore, PC61 significantly depleted populations of CD4+ T cells (p<0.05) and CD8+ T cells (p<0.01) in the tumor draining lymph nodes." (PMID 18431473, 2008). "Although primary CD8+ T-cell responses have been shown to be generated in the absence of CD4+ T cells, CD4+ T cells appear to be required for the generation of effective anti-tumour memory CD8+ T cells in many systems." (PMID 17505510, 2007). "The induction of tumor immunity described here requires CD8+, CD4+ T and NK cells." (PMID 18070359, 2007). "Claudin 7 is expressed on CD4 T-lymphocytes, and downregulated in tumor progression, but not previously identified in glia." (PMID 18088439, 2007). "In our study, effective anti-tumour memory CD8+ T-cell responses were observed in mice lacking CD4+ cells." (PMID 17505510, 2007). "Local PDT treatment led to enhanced anti-tumour immune memory that was evident 40 days after tumour treatment and was independent of CD4+ T cells." (PMID 17505510, 2007). "The number of either CD4+ or CD8+ T cells present in untreated right tumour did not change when the left tumour was surgically removed." (PMID 17505510, 2007). "This CD4+ T cell response, which is essential for tumour rejection in 100% of the mice, is not apparent unless the antibody is administered." (PMID 17294404, 2007). "In all patients, tumour grade was directly associated with Ki-67 labelling index (P<0.001), COX-2 expression (P<0.001), CD4+ (P<0.01) and CD8+ (P<0.001) T-lymphocytes, but not with C-reactive protein (P=0.152)." (PMID 17024120, 2006). "In one study that generated tumour-specific CD8+ cytotoxic T cells from allogeneic donors, MLTCs were initiated with a highly purified population of CD8+ donor lymphocytes potentially underestimating the role of CD4+ clones in the immune response." (PMID 16819544, 2006). "Most tumours do not express HLA class II molecules on their surface but HLA class II restricted CD4+ T cells are nevertheless considered to be mandatory for establishing and maintaining a clinically efficient anticancer immune response." (PMID 17060934, 2006). "Only the co-transfer of both CD4+ and CD8+ cells was capable of inducing tumor inhibition." (PMID 16725035, 2006). "It is known that tumor cells secrete immunosuppressive cytokines such as IL-10 and TGF-β, and the cytokines may induce CD4+CD25- lymphocytes to convert to CD4+CD25+ TR cells." (PMID 15679891, 2005).
tumor (continued). "Because a combination of CD4 and CD8 responses is required for sustained memory and antitumour activity, a panel of T-cell clones is probably needed to address the genetic and antigenic heterogeneity of tumour cells." (PMID 15700041, 2005). "Although proper activation of DCs for induction of CTL responses can be achieved by both CD4+-dependent and independent pathways, the help of Th epitopes and CD4+ T-lymphocytes has been shown to be crucial in optimising CTL responses and for efficient and long-lasting immunity against tumours." (PMID 15812545, 2005). "Ex vivo manipulation of T cells following exposure to immunomodulatory cytokines or selective depletion of regulatory cells (e.g. CD4, CD25+ T cells) may facilitate the isolation and expansion of tumor-reactive T cells for adoptive therapy." (PMID 15860133, 2005). "Thus, HHV8 is typically believed to infect B lymphocytes, epithelial cells, keratinocytes, KS tumor cells, and endothelial cells, while the predominant host cells for HIV-1 are CD4+ T lymphocytes, dendritic cells, and mononuclear phagocytes." (PMID 15713234, 2005). "Our observation that such sensitization occurred even in hosts with partial tumor regression indicates that the presence of effector CD4+ T cells and inflammatory conditions of tumor antigen acquisition by host APC are important in perpetuating the anti-tumor response." (PMID 15566571, 2004). "We have previously demonstrated that localisation of CD4+, CD8+ and CD57+ lymphocytes to sites of tumour is a requisite for the response to therapy, thus hypothesising that the antitumour activity of IFN-α in vivo is primarily cellular immune mediated." (PMID 14760375, 2004). "Depletion of NK cells in A/J mice with anti-asialo GM antibody did not induce tumour formation with viable N2A-IL-2+IL-12 cells, whereas depletion of both CD4+ and CD8+ T-cell populations resulted in aggressive tumour formation in all animals." (PMID 12771934, 2003). "In this way, besides direct tumour cell lysis by transduced CD8+ T cells, release of cytokines by transduced CD4+ T cells upon specific target cell interaction may also contribute to tumour growth inhibition as well as induction of NK/LAK activities." (PMID 12698199, 2003). "However, they performed a semiquantitative analysis of CD4+ and CD8+ lymphocytes at the periphery of the tumours and found that higher levels of infiltration of both were associated with reduced survival." (PMID 14612901, 2003). "The number and distribution of infiltrating CD4+ lymphocytes were similar in MSI and MSS tumours." (PMID 12232760, 2002). "Depletions of CD4+ or CD8+ cells did not affect (clone V3) or even slightly inhibit (clone V4) the progression of tumours having high Fas-L." (PMID 12177809, 2002). "Fas-Lribozyme reduced significantly the number of infiltrating granulocytes in tumour nodules of 96 h and 18 days after cell inoculation, but not the numbers of CD4+, CD8+ and NK cells." (PMID 12177809, 2002). "CD4+ T cells modulate the magnitude and durability of CTL responses in vivo, and may serve as effector cells in the tumour microenvironment." (PMID 11742496, 2001). "HER2/neu-derived peptides inducing MHC class II-restricted CD4+ T helper lymphocyte (Th) responses, although critical for tumour rejection, are not thoroughly characterized." (PMID 11720440, 2001). "However we observed the selective recruitment, localization and arrest of immune CD4+ and CD8+ T lymphocytes (P < 0.05) into the tumour microcirculation, and in some instances the subsequent extravasation of cells into the tumour interstitium." (PMID 10993655, 2000). "Tumour EBV status was related to EBV antibody titres, spontaneous and concanavallin A induced blood lymphocyte DNA synthesis, serum levels of soluble (s) CD4, sCD8, sCD25, sCD30, sCD54, β2-microglobulin, thymidine-kinase, routine chemistry, patient characteristics, complete remission and survival." (PMID 10584880, 1999).